TET2 (tet methylcytosine dioxygenase 2)
Diseases named in the same sentence as TET2 in open-access papers (continued):
Sharing a sentence is not in itself a finding about the gene and the disease.
leukemia (continued). "Besides HMA, our group has recently developed a new therapeutic approach which entails the use of a TET-selective small-molecule inhibitor able to selectively suppress TET2-mutant cells in mouse models and TET2-mutated human leukemia xenografts while sparing normal cells." (PMID 33808599, 2021). "Svct2 knockout in bone marrow cells expressing the AML oncogene Flt3ITD has also been shown to accelerate leukemia progression in mice and exacerbate 5hmC loss in Tet2 deficient HSCs, suggesting that vitamin C depletion could further impair the activity of other TET proteins in pre-leukemic cells." (PMID 34017357, 2021). "Vitamin C treatment in mouse models of leukemia was shown to mimic genetic restoration of Tet2 function, causing an increase in 5hmC formation, global DNA hypomethylation, a block in aberrant self-renewal and suppression of disease progression in Tet2-deficient mice." (PMID 31380368, 2019). "In the CTRL-ROY group, enrichment was significant for “leukemia” and “acute leukemia” terms (NES = 2.12, Q = 0.03), driven by key myeloid malignancy-associated genes DNMT3A, IDH1, SRSF2, and TET2." (PMID 41371958, 2026). "This TET2 activation improves cancer immunotherapy efficacy against renal cell carcinoma, regulates hematopoietic stem cell frequency, and reduces leukaemia occurrence." (PMID 41169875, 2025). "In leukemia models, vitamin C treatment has been shown to restore TET2 functionality, thereby inhibiting aberrant self-renewal and slowing leukemia progression." (PMID 40663150, 2025). "A previous study revealed that TET2 exerts tumour-suppressive effects by regulating cell cycle progression and promoting apoptosis in various cancer types, including leukaemia and solid tumours." (PMID 41169875, 2025). "Vitamin C administration restored TET2 activity, promoted DNA demethylation, and slowed leukemia progression in experiments with leukemia cell and mouse models." (PMID 40646353, 2025). "Inhibition of A20 expression can prevent TLR-TRAF6–primed TET2-mutant MDS from progressing to leukemia." (PMID 40111422, 2025). "This is supported by findings that Wilms’ tumor protein and Smad nuclear interacting protein 1 are indispensable for TET2 to suppress leukemia cell proliferation and regulate the cellular DNA damage response, respectively." (PMID 40459008, 2025). "Although m6A is firmly established as a central regulator of CSC functions, emerging data from NSUN7 in glioblastoma and TET2 in leukemia highlight the potential significance of m5C in maintaining CSC properties and promoting tumor progression." (PMID 41148823, 2025). "Restoration of TET2 function via vitamin C inhibits leukemia progression and maintains normal stem cell differentiation." (PMID 41516113, 2025). "We previously demonstrated that the loss of TRAF6 in BM cells with a deficiency of Tet2, which is the most frequently observed CHIP-associated mutation, results in transformation to leukemia in mice." (PMID 38609495, 2024). "For example, TET2 (idiopathic thrombocytopenic purpura [ITP]-related gene) was associated with Hodgkin’s lymphoma, leukemia, pneumonia, and purpura." (PMID 39009607, 2024). "TET2, ASXL1, DNMT3A, and SF3B1 are all known to harbor causal leukemia variants, and somatic variants in SRSF2 have been described in myelodysplastic syndrome." (PMID 39132489, 2024). "Contrastingly, in glioma and leukemia, IDH1 mutations that result in 2-hydroxyglutarate production disrupts TET2 function and establishes CIMP and global DNA hypermethylation." (PMID 37234978, 2023).
leukemia (continued). "Altogether, our work proposes that CEBPA-mutant AMLs acquire additional lesions in genes such as GATA2 and TET2 to reestablish balanced GATA2 levels that permit leukemia development and progression." (PMID 37794021, 2023). "Consistently, restoration of TET2 activity blocks aberrant self-renewal and leukemia progression, further supporting the vital role of TET2 in suppressing tumor development." (PMID 37550284, 2023). "Cluster 3 showed the highest leukemia burden, the shortest overall survival of patients, and the lowest 5hmC levels in the TET2 promoter." (PMID 37372359, 2023). "Altogether, our data suggest that loss of TET2 in CebpaDM AML causes a moderate decrease in Gata2 expression, which in turn increases the competitive fitness of the leukemia." (PMID 37794021, 2023). "Reduction of the TET2 gene led to increased TCM differentiation in a patient with leukemia who experienced a complete remission." (PMID 37467321, 2023). "Recently, it was suggested that SF3B1, SRSF2, ASXL1, TET2, and DNMT3A gene mutations contribute to the risk of MDS evolution to leukemia and also influence therapy response and overall survival." (PMID 36982819, 2023). "Severe deficiencies of TET2 and TET3 in HSPC lead to a loss of 5hmC of over 90%, leading to the spontaneous accumulation of DSB and further leading to the rapid progression of leukemia." (PMID 36979633, 2023). "Moreover, administration of Vit-C (1 mM) resembled TET2 recovery, by increasing 5hmC production in Tet2-deficient mice primary murine hematopoietic stem and progenitor cells (HSPCs), as well as suppressing human leukemic colony production and leukemia development in human primary leukemia." (PMID 35745630, 2022). "DNMT3A, TET2, and ASXL1 (“DTA”) mutations prevalently occur early in pre-leukemia hematopoietic stem and progenitor cells (HSPCs), persist for a long time and are not considered to be associated with poor prognosis." (PMID 35865470, 2022). "As chromosomal translocation partners, TET family members, including TET1 and TET2, were initially found in leukemia and proven to be key regulators of DNA demethylation owing to their dioxygenase activity." (PMID 35235761, 2022). "For example, a daily regime of high-dose Vit-C (4 g/kg) recovered TET2 activity in TET2-deleted animal mice with leukemia, resulting in increased DNA demethylation and the synthesis of the proteins necessary for the growth of myeloid cells." (PMID 35745630, 2022). "As such, it’s unclear to what extent TET2’s role in leukemia applies in the context of this immune disorder." (PMID 35393954, 2022). "TET2 recovery reverses the self-renewal of abnormal haematopoietic stem and progenitor cells in vitro and in vivo and inhibits leukaemia progression." (PMID 36684288, 2022). "Given that Tet2 and Dnmt3a are both epigenetic regulators, we speculate that the increased instability in epigenetic regulation combined with the presence of Flt3ITD/WT mutation likely facilitates the selection of a common set of dysregulated genes, which might contribute to leukemia development." (PMID 36073548, 2022). "Tet2 is dispensable for development, and Tet2 knockout mice grow normally to adulthood but develop leukemia later in life." (PMID 35235365, 2022). "A closer look into the mutations that persisted following therapy (at remission) in responders revealed that they were in genes associated with pre‐leukaemia (ASXL1, DNMT3A, IDH2, SRSF2 and TET2)." (PMID 36051087, 2022).
leukemia (continued). "The A1505T mutation in TET2 disrupts this interaction, consequently leading to an effect on WT1 target genes expression and increased leukemia cell proliferation." (PMID 33395407, 2021). "Taken together, the in vivo and in vitro results demonstrate that the loss of p300 enhanced the self-renewal and proliferation of Tet2-deficient HSPCs, increasing the bone marrow HSPC pool and accelerating leukemia development of the doubly deficient mice." (PMID 34622806, 2021). "Upon administering ascorbate to a FLT3ITD TET2+/- Gulo−/− murine model of leukemia, overall survival was prolonged and the progression of the disease was suppressed." (PMID 34497762, 2021). "Consistently, in acute myeloid leukemia (AML) cells with TET2 mutations, treatment with vitamin C mimicked TET2 restoration by increasing TET activity and blocked leukemia progression in patient-derived tumor xenograft models." (PMID 33804775, 2021). "Treatment with a TET-selective small molecule inhibitor has been found to suppress the clonal evolution of TET2 mutant cells in murine models and human leukemia xenografts." (PMID 34868917, 2021). "Vitamin C treatment also induces the expression of a TET2-dependent gene expression signature in human leukemia cell lines and primary murine HSPCs involved in BER such as GADD45, PARP, and DNA glycosylases." (PMID 34017357, 2021). "A clinical study on WT1-mutated AML refractory to induction chemotherapy suggested the use of vitamin C as adjunct therapy, based on the evidence that WT1 mutant leukemia cells show low 5hmC levels that in turn indicate reduced TET2 activity." (PMID 33804775, 2021). "Mice receiving DMSO-treated Tet2-null leukemia cells developed aggressive AML with severe anemia (4 weeks after transplantation), whereas recipients of I-CBP112–treated Tet2-null leukemia cells showed improved survival with less severe anemia." (PMID 34622806, 2021). "To test the effects of lysine acetylation on the catalytic activity of TET2 and its impact on the cellular proliferation, we treated different leukemia cell lines with several chemical probe that impact N- and C-terminal lysine acetylation." (PMID 32895473, 2020). "From clonal hematopoiesis to secondary leukemia of MDS, both TET2 and ASXL1 gene mutations are common in MDS and secondary leukemia patients." (PMID 33178287, 2020). "Previous studies on TETs in ESCs and reprogramming have showed that Vc can activate TETs as a cofactor, and a high dose of Vc has rescued TET2 deletion in a mouse model of leukemia." (PMID 32850862, 2020). "miR-22, a recognized oncogenic microRNA, is reportedly overexpressed in MDS and leukemia cells, negatively regulating TET2 mRNA levels." (PMID 32726753, 2020). "Previous studies indicate that treatment with vitamin C, a TET2 agonist, enhances TET2 activity in vivo, promoting DNA demethylation capacity and reversing aberrant self-renewal of leukemia initiating cells." (PMID 32726753, 2020). "In a mouse model of Tet2-dependent leukemia, treatment with vitamin C restored Tet2 activity in HSPCs." (PMID 32748835, 2020). "Accordingly, vitamin C-induced TET2 restoration overcame inhibitory effects of HDACi on DNA demethylation and enhanced anti-leukemia efficacy in vivo." (PMID 32726753, 2020). "In de novo AML with TET2 mutations hypermethylated promotor regions were found, overlapping with IDH1/2 mutated leukaemias." (PMID 31405121, 2019). "Restoration of TET2 function blocked aberrant self-renewal and leukaemia progression in chimeric mouse models." (PMID 31405121, 2019). "The Ten-Eleven Translocation-2 (TET2) enzyme activity is known to be enhanced in the presence of vitamin C (TET2 mutation is common in AML), and as such vitamin C has been reported to induce differentiation in leukaemia stem cells." (PMID 30695064, 2019).
leukemia (continued). "This study also identified immune disease-related genes associated with somatic mutations such as MYD88 and BCL10 in NF-κB signaling, CD79B, PAX5, and BCR in B-cell development, and MYH11, RUNX1, and TET2 in leukemia." (PMID 29937999, 2018). "Building on this information, three recent studies have explored the potential of ascorbate to restore normal cell function in mouse and cellular models of leukemia involving either mutant TET2 or IDH." (PMID 30018566, 2018). "As can be seen, there was not a single read among 55 reads in the nail DNA that showed the two basepair deletion in the TET2 gene which was present in 64 of 71 reads (VAF of 90%) in the leukaemia sample." (PMID 30213991, 2018). "As immune disease-related genes, MYD88 (81.4%) and BCL10 (25.9%) in NF-ĸB signaling, CD79B (59.2%), PAX5 (22.2%), and BCR (7.4%) in B-cell development, and MYH11 (25.9%), RUNX1 (7.4%), and TET2 (7.4%) in leukemia were observed." (PMID 29937999, 2018). "By contrast, combined Flt3ITD and Tet2/Idh2-mutant leukemia was found to be maintained and propagated by the MPP lineage–restricted progenitor population." (PMID 29355841, 2018). "Previously, the significance of TET2 expression in carcinogenesis was studied particularly for lymphomas and leukemias." (PMID 25557833, 2015). "Ten patients harbored alterations previously reported as somatically acquired variants, including in known leukemia genes (DNTM3A, TET2, and BCOR)." (PMID 28721364, 2015). "More recently, IDH mutations and resultant 2-hydroxyglutarate (2HG) production in leukemia cells were reported to induce global DNA hypermethylation through impaired TET2 catalytic function." (PMID 21829728, 2011). "In the most recently published research article in Nature, it has been demonstrated for the first time that the TET2 regulates the chromatin structure and leukaemogenesis in stem cells and leukaemia cells via MBD6 (binds 5-methycytosine residues in RNA) and NSUN2 (a RNA methylase)." (PMID 39757230, 2025). "Our study suggests that the use of curcuminoids in leukemia cells with wild-type or partially functioning TET2 could increase 5hmC levels and induce active demethylation of silenced promoter hypermethylated genes." (PMID 41516186, 2025). "GSEA from TET2-mutated samples supported this finding as ‘Regulation of cellular amino acid metabolic process’ was upregulated in AML HSPCs suggesting a distinct role of amino acids in specific leukaemias." (PMID 40664811, 2025). "In addition, the RNA demethylase TET2 functions in leukemia stem cells, where its depletion enhances self-renewal and migratory capacity, thereby accelerating leukemogenesis." (PMID 41148823, 2025). "In contrast, aggressive transplantation leukemia is observed in Flt3ITD/wt, Tet2+/−, and Dnmt3a+/− mice within the same time scale, mainly associated with quantitative rather than qualitative differences in gene expression relative to Tet2mut/ Flt3mut or Dnmt3amut/ Flt3mut mice." (PMID 39078434, 2025). "Although TET2 mutation alone is not enough to induce leukemia, TET2 loss in combination with FLT3-ITD mutation is found to be sufficient to induce AML in vivo." (PMID 38696033, 2024). "TET2-mutant human leukaemia becomes dependent on this gene activation pathway, with MBD6 depletion selectively blocking proliferation of TET2-mutant leukaemic cells and largely reversing the haematopoiesis defects caused by Tet2 loss in mouse models." (PMID 39358506, 2024). "Among these, TET2 mutations have not been shown to independently impact either overall or leukemia-free survival." (PMID 39759649, 2024). "GLUT3) promotes leukemia progression and impedes ten-eleven translocation 2 (TET2) restoration." (PMID 37107291, 2023). "Up to now, mutations in TET2 have not been proven to independently impact OS or leukemia-free survival in patients with CMML." (PMID 36409328, 2023).
leukemia (continued). "Indeed, mimicking TET2 restoration ascorbate treatment suppresses leukemic colony formation and leukemic progression of primary human leukemia patient-derived xenografts (PDX)." (PMID 35938170, 2022). "We and other previously presented numerous animal models for TET2-related leukemia." (PMID 35771283, 2022). "In addition, Vit-C promoted DNA hypomethylation and increased TET2-dependent gene expression in human leukemia cell lines." (PMID 35745630, 2022). "TET2 p.Ala304Val has only been previously identified in melanoma, while TET2 p.Phe868Leu has been previously identified in estrogen- and progesterone-receptor positive breast cancer, adult T cell lymphoma/leukaemia, and MDS." (PMID 35033063, 2022). "Moreover, AA was able to restore 5-hmC formation, drive DNA hypomethylation and expression of a TET2 gene signature, and ultimately suppressed leukemia progression in patient-derived xenografts (PDXs)." (PMID 33808599, 2021). "TET-selective small molecule inhibitor suppresses the clonal evolution of TET2 mutant murine cells, as well as human TET2-mutated leukemia xenografts without affecting the normal hematopoietic precursor cells in vitro and in vivo." (PMID 34771553, 2021). "Clonal hematopoiesis of indeterminate potential (CHIP) in leukemia associated genes including DNMT3A, ASXL1, TET2 with a variant allele frequency (VAF) of ≥2% can confer a predisposition for hematological malignancy including overt leukemia, as well as thrombosis, stroke and cardiovascular events." (PMID 34639121, 2021). "TET2/DNMT3A was co-mutated in human lung, breast, skin and kidney cancers and frequently in angioimmunoblastic and peripheral T cell lymphomas and several types of leukemia." (PMID 34039392, 2021). "Likewise, MAGI2-AS3 impairs leukemia stem cells’ self-renewal through recruitment of TET2 (Tet methylcytosine dioxygenase 2, involved in cytosine demethylation) to the LGIR1 promoter." (PMID 34503076, 2021). "Furthermore, ascorbate treatment has been shown to mimic TET2 activities and suppress human leukemic colony formation and leukemia progression of primary human leukemia PDXs." (PMID 33673398, 2021). "We next evaluated the effect of I-CBP112 on the growth of Tet2-null leukemia cells in vivo." (PMID 34622806, 2021). "CHIP is driven by somatic mutations in leukaemia driver genes, such as Janus Kinase 2 (JAK2), Tet methylcytosine dioxygenase 2 (TET2), ASXL Transcriptional Regulator 1 (ASXL1) and DNA (cytosine-5)-methyltransferase 3A (DNMT3A), leading to reduced diversity of the blood pool." (PMID 32526214, 2020). "Similarly, in human leukemia cells, vitamin C suppresses proliferation and induces a TET2-dependent gene signature." (PMID 32748835, 2020). "A recent report indicated that a member of EGR family, WT1 (Wilms tumor suppressor gene 1) may recruit TET2 to demethylate its binding sites in leukemia cells." (PMID 31467272, 2019). "Vitamin C can restore and enhance TET2 enzymatic activity to suppress leukemia." (PMID 31001476, 2019). "TET2 loss-of-function mutations were identified in myeloid and lymphoid hematological malignancies, whereas the TET1 overexpression found in mixed lineage leukemia (MLL)-rearranged leukemia is oncogenic." (PMID 28032215, 2017). "Somatic mutations of several epigenetic modulators (DNMT3A, TET2, IDH1/2) occur frequently among patients with pre-leukemia diseases such as MDS and apparently healthy individuals with clonal hematopoiesis or CHIP, an aging-related phenotype associated with increased risk of AML." (PMID 29075615, 2017). "Consistent with the idea that TET2 may play a role in leukaemia, Tet2 mutant mice show increased hematopoietic stem cell self-renewal and myeloid transformation." (PMID 28130413, 2017). "While loss of TET1 and TET2 expression is associated with solid cancers, implying a tumor suppressor role, TET1 exhibits a clear oncogenic role in the context of genomic rearrangements such as in MLL-fusion rearranged leukemia." (PMID 26869355, 2016).